MMP9 (matrix metallopeptidase 9)
Diseases named in the same sentence as MMP9 in open-access papers (continued):
Sharing a sentence is not in itself a finding about the gene and the disease.
cancer (continued). "MMP‐9 also acts as a sheddase to proteolytically trim cell surface proteins in both immune cells and cancer cells." (PMID 34486239, 2021). "TC counts and MMP9 expression in para-cancer tissues were significantly higher in samples of patients with metastasis than in those of patients without metastasis." (PMID 34376644, 2021). "Results reveal that MMP9 and IL-6 secretion was significantly upregulated in response to all cancer EVs, relative to untreated cells, while the amount of MMP9 or IL-6 induced was dependent on the cancer cell secreting the EVs." (PMID 33984826, 2021). "As a continuation, in this present study, the partitions of n-hexane of AC and n-hexane and ethylacetate of IC were selected for the determination of IC50 against MMP9 as well as against four types of cancer cell lines, namely, MDA-MB-231, 4T1, T47D, and MCF7." (PMID 33800366, 2021). "MMP-9 is one of the key proteases involved in many cancer processes, such as angiogenesis, invasion, and metastasis." (PMID 34822465, 2021). "MMP-9 plays a critical role in angiogenesis, immune cell migration, activation of cytokines and chemokines, and progression and metastasis of cancer cells." (PMID 33707590, 2021). "Activation of miR‐21 also increases the expression of MMP-2 and MMP-9, known cancer markers involved in invasion, metastasis and angiogenesis of cancer." (PMID 33863340, 2021). "We first revealed that an NEDD8-activating enzyme inhibitor exhibits an inhibitory effect on the TNF-α-induced activity of MMP9 in ESCC cells and therefore suppresses MMP9-dependent cancer cell migration." (PMID 33572115, 2021). "The present results first confirmed that abnormal MMP-9 expression contributes to cancer cell proliferation and invasion of chemoradiation resistant NPC." (PMID 33390772, 2021). "According to previous reports, the MMP9 gene acts as an important oncogene and promotes cancer progression in HCC." (PMID 34239873, 2021). "CD44 promotes cancer cell migration and invasion by directly interacting with MMP-9, which degrades collagens." (PMID 34685653, 2021). "Loss of the protein expression of E-cadherin is a well-established characteristic of invasive epithelial cancers, and MMP-9 plays key roles in regulating local invasion during cancer progression." (PMID 34073071, 2021). "MMP-2 and MMP-9 are enzymes that play an important role in basement membrane degradation, which is the first step in the invasion and metastasis of cancer cells." (PMID 34589307, 2021). "The serum concentrations of MMP-2 and MMP-9 differ significantly regarding age, presence of microcalcification, irregular shape, diameter or number of cancer foci, and other clinicopathological features mentioned earlier." (PMID 34684168, 2021). "Knockdown of Kindlin-2 has been reported to lead to a significant reduction in the invasive properties of cancer cells through nuclear factor kappa B (NF-κB)-dependent upregulation of the expression of matrix metallopeptidase (MMP)-9 and MMP-2." (PMID 34338144, 2021). "In a subsequent study, the same group showed that lidocaine-related inhibition of TNFα-induced, Src-dependent signalling in lung adenocarcinoma cells resulted in reduced MMP-9 expression and reduced cancer cell invasion." (PMID 34408981, 2021). "The known downstream targets of β-catenin, including MMP-9, c-Myc, cyclin D1, etc., are mainly responsible for β-catenin-driven malignancy in cell proliferation, cell cycle progression, and metastasis in cancer biology." (PMID 34545072, 2021). "MMP9 gene is a member of the matrix metalloproteinase family and involves in metastasis of cancer cells." (PMID 33564285, 2021).
cancer (continued). "Both MMP-2 and MMP-9 contribute to various processes in cancer including invasion, metastasis, and angiogenesis." (PMID 34654351, 2021). "This MMP isoform is strongly overexpressed in the metastatic microenvironment, where it plays a central role by activating MMP-9 and osteolysis, resulting in the release of growth factors that further stimulate cancer cell proliferation." (PMID 33498946, 2021). "S100A11 and MMP-9 were both highly expressed in the serum of patients with EOC and were associated with cancer development, invasion, and metastasis." (PMID 33763485, 2021). "Possible mechanism of circLMNB1 (hsa_circ_0127801) includes upregulation of MMP-2, MMP-9, and N-cadherin expression, which are related to the primary mechanism of cancer cell invasion and metastasis, and EMT." (PMID 34298612, 2021). "EBF1 inhibits IL-6 expression leading to the inhibitions of Jak-STAT, RAS and MAPK signaling pathways as well as COX-2 and MMP-9 expressions resulting in the inhibition of cancer progression." (PMID 33854627, 2021). "The NET-associated proteases, neutrophil elastase (NE) and matrix metalloproteinase 9 (MMP-9), cleaved laminin, resulting in the proliferation of dormant cancer cells by activating integrin signaling." (PMID 34572138, 2021). "JNK1/2 inhibition or c-Jun depletion reduced expression of matrix metalloprotease (MMP)-9, a crucial enzyme involved in cancer cell invasion." (PMID 33303976, 2021). "In 3D in vitro model, monocyte MMP-9 secretion induces EC tight junction zonula occludens-1 (ZO-1) and occludin disruption, thus enhancing cancer cell extravasation." (PMID 33783686, 2021). "MMP-2 and MMP-9 are important enzymes responsible for degradation of the extracellular matrix, resulting in cancer cell migration and invasion." (PMID 33958506, 2021). "Two molecular mechanisms underlying the interactions between HCC cells and TCs account for the regulation of MMP9 expression and the mechanism by which TCs accelerate cancer cell metastasis." (PMID 34376644, 2021). "MMP‐9 is one of the most widely studied and well‐documented MMPs in cancers which has been determined to be involved in several biological processes, especially take a part in extracellular matrix (ECM) degradation." (PMID 34096173, 2021). "These exosomes increased CD44 expression in HPMCs, which facilitated cancer invasion by inducing the HPMCs to secrete matrix metalloproteinase-9 (MMP9)." (PMID 34680456, 2021). "By gelatin zymography, we detected the pro-forms of matrix metalloproteinases MMP-2 and MMP-9 in the conditioned media of MB49 cancer cells cultured in vitro." (PMID 34199232, 2021). "Because IL‐33 and MMP‐9 are often highly expressed in various tumors, this immunosuppressive mechanism most likely exists in other cancer types." (PMID 34486239, 2021). "In this article, we concentrated on MMP-2 and MMP-9, due to their high expression reporting by various cancers investigations including CRC." (PMID 34337054, 2021). "AR, Ki67 and HF1beta were more strongly expressed in cancer cells than in stroma, VEGF was almost equally expressed in both, while MMP9 was more strongly expressed in stroma than cancer cells." (PMID 33920263, 2021). "Out of 24 MMPs, MMP9 is the only one that is undetectable in healthy tissues and highly expressed in inflammation and in several diseases, including cancer." (PMID 33466421, 2021). "Through Spearman’s statistical analysis, we found that MMP9 expression was positively correlated with TC count in HCC para-cancer tissues, and that TCs also secreted MMP9 in vivo." (PMID 34376644, 2021). "This is not very surprising, as these pathways are commonly used by growth factors to induce MMP-9 expression in cancer cells." (PMID 34198494, 2021). "Salivary MMP-9 and 8-OHdG of cancer cases according to the location, TNM staging, and follow-up after surgery." (PMID 33735248, 2021).
cancer (continued). "Upregulation of MMP-9 has been shown to facilitate cancer progression, invasion, and development of metastases in various types of human malignancies." (PMID 34684168, 2021). "As shown in our study, stromal macrophages are better biomarkers of cancer progression in case of MMP9." (PMID 33920263, 2021). "At the same time, the expression of MMP2, MMP7, and MMP9 (factors in the matrix metalloproteinases family and involved in the invasion of cancers) was detected in the control cells and HCT116-Id4 cells." (PMID 33936204, 2021). "Matrix metalloproteinase 9 (MMP9) is involved in several aspects of the pathology of cancer, including invasion, metastasis, and angiogenesis." (PMID 34577904, 2021). "MMP2 and MMP9 belong to the metzincin superfamily and contribute to the pathogenesis of cancer cell invasion." (PMID 34484336, 2021). "In HeLa carcinoma cells, MMP9 expression is activated by phorbol esters that induce MEK-1-and NFκB, whose binding stimulates release of corepressor complexes that constitutively bind MMP9 in unstimulated cells." (PMID 33732255, 2021). "Similar to connective tissue homeostasis and cancer metastasis, Hyal-2 OEx by trophoblast cells induced both zymogen as well the mature form of MMP-9 in a similar pattern to that previously demonstrated in vitro." (PMID 33208556, 2020). "Benztropine significantly inhibited in vitro tumoroid formation, cancer cell survival, and MMP9 promoter activity." (PMID 32102440, 2020). "MMP9, Matrix Metallopeptidase 9, plays a role in the breakdown of extracellular matrix during cancer metastasis." (PMID 32986937, 2020). "MMP-9 is well-studied matrix metalloproteinase which plays an important role in promoting the malignant behaviors of cancer cells." (PMID 33224866, 2020). "In contrast, the CV extract-stimulated MCF-7 cancer cells only released higher levels of IL-6 compared to untreated cells, while the concentrations of IL-8 and MMP-9 were comparable with the control cells (respectively)." (PMID 33260615, 2020). "It is known that MMP2 and MMP9 can degrade gelatin and Type IV collagen, and break the barriers so that cancer cells can traverse to metastasis." (PMID 33442480, 2020). "Notch1 signaling increases the DNA binding ability of NF-κB and thereby induces the expression of MMP9, which remodels the extracellular matrix and facilitates the extravasation of several cancer cells." (PMID 32517366, 2020). "The members of the MMP family like MMP-2 (gelatinase -A) and MMP-9 (gelatinase-B) remain up-regulated in malignant tumors." (PMID 33112542, 2020). "The rational for the use of AMD3100 in oncology is that CXCR4 binding by natural ligands, such as the CXCL12 chemokine, triggers PI3K/AKT, thereby promoting MMP-9 expression and cancer cell invasion/dissemination." (PMID 32630531, 2020). "What is more, it is shown that MYC also promote the expression of MMP9, VEGF, HIF-1α, and TGF-β (all genes associated with cancer aggressiveness) in TAM." (PMID 33081056, 2020). "For their part, activated macrophages release MMP-9 which further remodels the structure of local ECM to favor the homing of disseminated cancer cells at distant sites." (PMID 32630531, 2020). "In this context, it should be considered that the flexibility of the MMP-9 linker region connecting the catalytic and hemopexin domains optimizes the interaction of migrating cancer cells with MMP-9 substrates." (PMID 32630531, 2020). "MMP-9 can directly affect the invasion of cancer cells and has proangiogenic and growth-promoting functions in brain tumors through the release of ECM growth factors." (PMID 31900168, 2020). "It is worthy of note that HIV protease inhibitors such as ritonavir, saquinavir, indinavir and lopinavir strongly reduce MMP-9 expression and/or activity in normal or cancer cells and in treated patients." (PMID 32630531, 2020). "M2 macrophages produce high levels of MMP-9, which is an important player in cancer progression, because it degrades the extracellular matrix." (PMID 32660099, 2020).
cancer (continued). "For example, MMP2, MMP3, and MMP9 are direct or indirect target genes of FoxO3a in endothelial as well as cancer cells, and FoxO4 upregulated MMP9 expression in smooth muscle cells stimulated by tumor necrosis factor‐α (TNF‐α) by an indirect mechanism." (PMID 32790044, 2020). "The promotion of cancer metastasis by MMP‐9 through EGFR‐mediated signaling pathway has been addressed." (PMID 32180962, 2020). "MMP9 is one of the markers for aggressive tumors; in his study, Sogawa reported that Benz inhibited the expression of MMP9, also reducing cancer metastases and angiogenesis." (PMID 32867142, 2020). "Both extracts were shown to prolong doxorubicin retention time in cancer cells, while the application of doxorubicin/extract combination led to a decrease in MMP9 expression." (PMID 33182665, 2020). "The interaction of LCN2 with MMP-9 seems to play a crucial role in the modulation of the metastatic phenotype of cancer cells." (PMID 32575507, 2020). "Other molecules described to be expressed in neutrophils in the cancer niche are MMP-9, IL-4, and IL-10 (although very controversial)." (PMID 32117288, 2020). "Particularly, MMP-9, a key member of the MMP family, is linked to metastasis in a variety of cancer types." (PMID 32158355, 2020). "The functions of MMP-9 are the regulation of cancer progression, angiogenesis, and recruitment of macrophages or other bone marrow-derived myeloid cells to the existing metastatic niche." (PMID 32013255, 2020). "In the present study, a high expression of MMP-9 in cancer tissues was observed by immunohistochemistry, and there was a positive correlation with the increase of CXCL8 expression." (PMID 32201645, 2020). "Intriguingly, TGFβ1 secreted by TAMs also increased expression of MMP9 in glioma stem-like cells that contributes to the invasive ability of these cancer stem cells." (PMID 32283687, 2020). "MMP-9 is highly expressed in non-small cell lung cancer, cervical cancer, ovarian cancer, and pancreatic cancer and can be used as a biomarker in cancer prevention and diagnosis." (PMID 32698816, 2020). "It has been known that matrix metalloproteinase-2 (MMP-2) and matrix metalloproteinase-9 (MMP-9) can promote the migration of cancer cells and facilitate extracellular matrix degradation." (PMID 33046984, 2020). "ALDH1A1 expression was positively correlated RARα with Ets1 and metalloproteinase 9 (MMP9) was one of the most important substance related to cancer invasion and metastasis." (PMID 32984354, 2020). "MMP-9 is the key direct regulator of cancer angiogenesis and affects neovascularization in numerous manners." (PMID 32117712, 2020). "MMP9 is a prognostic marker for several cancers, with several studies showing its role in angiogenesis, extracellular matrix and surface receptor cleavage." (PMID 32655131, 2020). "In fact, increased MMP-9 levels in cancer patient serum correlates with the probability of metastatic spread." (PMID 32948029, 2020). "MMP-9 is a type IV collagenase which is commonly overexpressed and upregulated in the epithelium of cancer cells." (PMID 32328465, 2020). "MMP-2 and MMP-9 are enzymes involved in prostatic development and growth, important to cancer progression." (PMID 33013201, 2020). "In this work, we aimed to compare the potential anti-cancer and MMP-9 inhibitory activities between these two well-known Aloe species, A. vera and A. arborescens." (PMID 33308217, 2020). "It has been reported that MMP2 and MMP9 cause the proteolysis of ECM components and induction of cancer cell invasion." (PMID 32266797, 2020). "Several studies have indicated that transcription factors (e.g., those in the AKT/β-catenin pathways) are involved in regulating the activities of MMP2 and MMP9 and thus cancer cell metastasis." (PMID 33371405, 2020). "As vividly shown in the picture, LCN2 had strong physical interactions with MMP-9, which is crucial in cancer metastasis." (PMID 33425761, 2020).
cancer (continued). "Activated neutrophils, in turn, release TIMP-1-free MMP-9, which effectively aids cancer cells to breach blood vessel walls." (PMID 32630531, 2020). "NE and MMP-9, which are enzymes associated with NETs, can cleave the extracellular matrix (ECM) leading to integrin-mediated signaling, which awakens dormant cancer cells and promotes cancer cell growth." (PMID 32849639, 2020). "Among various subtypes of MMP proteins, MMP-2 and MMP-9 are frequently found to be related with cancer cell invasion and aggressiveness." (PMID 32155880, 2020). "SPOCK1 is a secreted proteoglycan reported to induce EMT in several cancer cell lines and up-regulate the expression and activity of MMP-9 24–26,37,38." (PMID 32555336, 2020). "It is important to note that MMP-9 secretion is elevated in several types of human cancer, and such elevation is correlated with poor prognosis." (PMID 33520928, 2020). "Further efforts have been specifically directed against MMP-9, considering the impact that this enzyme has on cancer metastasis." (PMID 32630531, 2020). "As PI3K/Akt pathway has been reported to be involved in cancer cell invasiveness and MMP9 and VEGF regulation, we tested the involvement of this pathway in our system." (PMID 32205867, 2020). "We also discuss the biological and molecular consequences of LCN2 dysregulation in many tumor types, and we explain how its interaction with MMP-9 promotes cancer cell growth and metastasis." (PMID 32575507, 2020). "eIF4E is overexpressed in cancer and exerts oncogenic potential by regulating mRNAs related to proliferation (c-Myc, CDK2, and Cyclin D1), metastasis (MMP9 and heparanase), loss of apoptosis (Mcl-1, Bcl-2, and survivin), and angiogenesis (VEGF and FGF2)." (PMID 32967226, 2020). "MMP9 is a proteolytic enzyme belonging to MMP superfamily that lowers the value of the extracellular matrix (ECM) causing angiogenesis and cancer cell migration." (PMID 33066411, 2020). "In recent years, the importance of cancer-associated proteases such as matrix metalloproteinases MMP-2 and MMP-9 in invasion and metastasis has been reported for a variety of solid malignant tumors." (PMID 33348592, 2020). "Some of these characteristics are the result of LCN2′s ability to facilitate iron intake to cancer cells or its ability to form a heterodimer with MMP-9." (PMID 32575507, 2020). "The positive expression of MMP9 indicates the low survival rate of small hormone reactive tumors, and its expression in cancer cells is beneficial to the survival of tumors." (PMID 32849897, 2020). "MMP-9 produced by neutrophils can trigger the growth of dormant cancer cells by remodeling extracellular matrix and releasing potent angiogenic factors." (PMID 32849639, 2020). "The expression of cellular EMT marker changes, including MMP‐9, vimentin and E‐cadherin, has implications for the cancer invasion‐metastasis process." (PMID 32294802, 2020). "PlGF has an important role in tumor angiogenesis, although a stimulatory effect was also reported for MMP-9-mediated NSCLC cancer cell invasion." (PMID 32503281, 2020). "Overexpression of MMP-9 is often observed in different malignant tumors and has been shown to promote metastasis and invasion by inducing angiogenesis and BM degradation." (PMID 32047820, 2020). "MMP-2 and MMP-9 degrade the extracellular matrix, playing an important role in cancer cell invasion, metastasis, and angiogenesis, which are impacted by EMT formation." (PMID 33062005, 2020). "According to an analysis of a public data base, MMP-9 acts in a context-dependent manner in different types of cancer." (PMID 33046030, 2020). "MMPs play critical functions in cancer progression and in particular, MMP-9 has been shown to play a major role in cancer cell migration and invasion." (PMID 32328465, 2020). "HDAC8 also is involved in cellular invasion and expression of the MMP-9 gene in human cancer cells[30 ▶]." (PMID 32429642, 2020).